RNU6-323P (RNA, U6 small nuclear 323, pseudogene)
Gene: Small nuclear RNA gene on chromosome 8 (38,166,012 to 38,166,118, reverse strand). Ensembl gene ENSG00000253739.
Homologues: Orthologues: chimpanzee U6 (98% identical). Paralogues in human: RNU6-128P (90% identical), RNU6-144P (88% identical), RNU6-15P (88% identical), RNU6-26P (88% identical), RNU6-1 (87% identical), RNU6-2 (87% identical), RNU6-207P (87% identical), RNU6-21P (87% identical), RNU6-38P (87% identical), RNU6-3P (87% identical), RNU6-4P (87% identical), RNU6-5P (87% identical), and 1292 more.